FGFR2 (fibroblast growth factor receptor 2)
Diseases named in the same sentence as FGFR2 in open-access papers (continued):
Sharing a sentence is not in itself a finding about the gene and the disease.
Apert syndrome (continued). "Fgf10 mRNA is present in the osteoprogenitors in the frontal bone condensation, and genetic knock-down of Fgf10 rescues the skeletal phenotype in an Apert syndrome mouse model FgfR2-IIIc+/Δ." (PMID 30505318, 2018). "This confirms the resistance of the mouse to FGFR2-related limb defects, similar to mouse models for Apert syndrome (AS) that have normal limbs." (PMID 28069589, 2017). "Gain-of-function mutations of FGFR2 and FGFR3 cause Apert syndrome and thanatophoric dysplasia, which are characterized by unique and complex malformation of the cortex, including megalencephaly and polymicrogyria." (PMID 28489004, 2017). "Members of two families with an index case of Apert Syndrome were assessed to describe relevant clinical features and molecular analysis (sequencing and amplification) of exons 8, 9 and 10 of FGFR2 gen." (PMID 26600631, 2015). "We examine late embryonic skull development and suture patency in Fgfr2 Apert syndrome mice between embryonic day 17.5 and birth and quantify the effects of these mutations on 3D skull morphology, suture patency and growth." (PMID 24580805, 2014).
Apert syndrome (continued). "Our Apert syndrome mouse models are heterozygotes, so cells expressing Fgfr2 receptors have both normal and mutant receptors, the latter of which lead to aberrant Fgfr2 activation by modifying ligand affinity and specificity." (PMID 22053191, 2011). "The mechanism underlying the exquisite genotype-phenotype correlation of Apert syndrome mutations needs to be understood in terms of the biology of FGF/receptor signalling and the structural pathophysiology of FGFR2 mutations." (PMID 21943124, 2011). "Based on the known pathogenesis of Apert syndrome, the chimeric FGFR2 protein is predicted to act in a dominant gain-of-function manner." (PMID 21943124, 2011). "For example, recent studies of a mouse model for Apert syndrome, with a single amino acid change in FGFR2, support the notion that enhanced activation of FGFR2 can cause some cranial mesenchyme to convert to a chondrocyte differentiation program." (PMID 16504022, 2006). "FGFR2 is predominantly expressed in the cartilages of the cranial base and epiphyseal dysplasia, as well as in differentiating osteoblasts and osteoprogenitor cells of the chondrocyte lineage in Apert syndrome." (PMID 40261605, 2025). "HRS has been occasionally reported in FGFR2‐related Pfeiffer and Apert syndromes." (PMID 40673520, 2025). "We report on the clinical and molecular assessment of FGFR2 in six Apert syndrome patients from six Egyptian families, highlighting the importance of raising awareness about the cardinal phenotype of AS and informing physicians about variability and genetic counseling decisions." (PMID 40261605, 2025). "Prenatal diagnosis of Apert syndrome has transitioned from isolated anomaly detection to a molecularly integrated paradigm, where recognition of the sonographic triad is synergistically enhanced by fetal MRI biomarkers and rapid FGFR2 sequencing." (PMID 41268110, 2025). "In some of the FGFR2-associated disorders, the phenotypic spectrum includes skin lesions, such as cutis gyrata in Beare–Stevenson cutis gyrata syndrome (BSTV; MIM 123790) or acne in Apert syndrome (MIM 101200)." (PMID 38265560, 2024). "We recommend undertaking specific searches for this type of mutation in patients with typical Apert syndrome and without coding variants in FGFR2." (PMID 38318288, 2023). "The objectives of this review are to clarify the palatal phenotypes in patients with Apert syndrome as well as in mouse models of Apert syndrome, and discuss the signaling pathways downstream of FGFR2 in palatogenesis to further understand the pathogenesis of cleft palate in Apert syndrome." (PMID 35997397, 2022). "Palatal defects in Apert syndrome make evident the critical role of FGFR2 in palatogenesis." (PMID 35997397, 2022). "Moreover, the loss of delayed receptor internalization and lysosomal FGFR2 degradation plays a major role in the increased FGFR2 signaling activity in Apert syndrome." (PMID 34829964, 2021). "The FGFR2 inducibility of epithelial acne—whether sporadic (ligand-induced) or in Apert syndrome (constitutive)—is attributable to hyperactivation of FGFR2b." (PMID 34007277, 2021).
Apert syndrome (continued). "The FGF receptors FGFR2 and FGFR3 show striking paternal age effects for the specific mutations that cause Apert's syndrome and achondroplasia, respectively, and these mutations show compelling evidence for clonal expansion of SSCs through inappropriate FGF signalling." (PMID 33107118, 2021). "Nevertheless, it is instructive to consider the Apert syndrome model, in which the mice are hemizygous for Fgfr2 IIIC and exhibit a splicing switch resulting in ectopic expression of FGFR2 IIIb in calvarial mesenchyme; similar mutations are only rarely found in humans." (PMID 30505318, 2018). "As previous described, our mice were likely to exhibit effects of the mutant FGFR2 on endochondral ossification, showing skull malformations and shortening of the anterior–posterior axis similar to bone defects seen in patients with Apert syndrome." (PMID 24489893, 2014). "Our results confirm that despite severe craniofacial dysmorphologies, mice carrying Apert syndrome Fgfr2 mutations share MI patterns with their non-mutant littermates, but show increased integration, providing evidence to reject Ho and support H1B." (PMID 22053191, 2011). "It is known that gain of function (GOF) mutations in FGFR2, primarily in the III Ig-like domain and the adjacent linker regions (exons IIIa and IIIc), can cause several different types of autosomal dominant craniosynostosis, including Crouzon syndrome, Pfeiffer syndrome, and Apert syndrome." (PMID 38098042, 2023). "Moreover, mutations in FGFR1 and FGFR2 genes have been established in the pathogenesis of some syndromes in which clefts are present, such as Apert syndrome (FGFR2), Crouzon syndrome (FGFR2, FGFR3), Hartsfield syndrome (FGFR1) and Kallmann syndrome (FGFR1, FGF8)." (PMID 35455561, 2022).
Apert syndrome (continued). "In the FGFR2 gene (OMIM: *176943), five patients were diagnosed with Apert syndrome (OMIM: 101200), two with Crouzon syndrome (OMIM: #123500), and one with Pfeiffer syndrome (OMIM: 101600)." (PMID 40130161, 2025).
intrahepatic cholangiocarcinoma (94 papers, 2014 to 2026). A carcinoma that arises from the intrahepatic bile duct epithelium in any site of the intrahepatic biliary tree. "Although FGFR1 or FGFR2 amplifications and mutations are frequent in non-small cell lung, breast, endometrial and gastric cancer, intrahepatic cholangiocarcinoma is more prone to have FGFR2 gene fusions." (PMID 41361008, 2026). "Fibroblast growth factor receptor-2 (FGFR-2) mutations are frequently observed in intrahepatic cholangiocarcinoma (ICC)." (PMID 40255433, 2025). "For instance, mutations in the IDH1 and IDH2 genes, as well as alterations in the FGFR2 gene, are more commonly associated with intrahepatic cholangiocarcinoma." (PMID 40075667, 2025). "This study explored the association of FGFR2 status with the prognosis and immune cell infiltration profiles of patients with intrahepatic cholangiocarcinoma." (PMID 38986528, 2024). "Except for gene fusions, FGFR2 genetic alterations in intrahepatic cholangiocarcinomas (ICCs) have received limited attention, leaving patients harboring activating FGFR2 gene mutations with inadequate access to targeted therapies." (PMID 37964396, 2023). "Across several compounds, FGFR2 fusions were most sensitive in intrahepatic cholangiocellular carcinoma (ihCC) and FGFR3 mutations showed the best responses in urothelial cancers." (PMID 36231142, 2022). "FGFR2 rearrangements/mutations occur in 12–17% of intrahepatic cholangiocarcinoma, resulting in increased cell proliferation, tumor growth and metastatization." (PMID 35055006, 2022). "While FGFR2 alterations and FGFR2 fusion proteins have been identified as drivers of intrahepatic cholangiocarcinoma, FGFR1 fusion proteins are implicated as drivers of stem cell leukemia/lymphoma." (PMID 35574218, 2022). "Activating mutations and gene fusions involving FGFR2 were mutually exclusive with these and identified in 4% and 10–15% of intrahepatic bile duct carcinomas, respectively." (PMID 35871236, 2022). "BRCA2, CDKN2A, and FGFR2 mutations were most frequently identified in case of intrahepatic cholangiocarcinoma." (PMID 34316332, 2021). "Point mutations in the FGFR2 kinase domain were also found in FGFR2 fusion-positive intrahepatic cholangiocarcinoma (ICC)." (PMID 34830951, 2021). "In a recent study in patients with fluke associated-intrahepatic cholangiocarcinoma, the presence of rare FGFR2 fusions indicated a trend toward better OS compared with that of fusion-negative tumors, although the difference was not statistically significant." (PMID 32962091, 2020). "The presence of FGFR genomic alterations, including FGFR2 fusions genes identified by NGS in 55 patients with intrahepatic cholangiocarcinoma, has been associated with an indolent disease course and prolonged survival." (PMID 32962091, 2020). "Some progress has been made with the identification of isocitrate dehydrogenase (IDH) mutations and fibroblast growth factor receptor 2 (FGFR2) fusions as drivers in small subsets of intrahepatic cholangiocarcinoma tumors." (PMID 30815737, 2019). "In BTCs, especially intrahepatic cholangiocarcinoma, comprehensive molecular profiling has expanded precision oncology through actionable alterations such as FGFR2 rearrangements, IDH1 mutations, HER2 amplification/overexpression, BRAF V600E, NTRK fusions, and MSI-high/dMMR status." (PMID 42196390, 2026). "Furthermore, FGFR2 overexpression is linked to a poor diagnosis and treatment response, and its rearrangement or fusion is concentrated in intrahepatic cholangiocarcinoma." (PMID 38702814, 2024). "For instance, a substantial percentage of intrahepatic cholangiocarcinomas have been shown to bear mutations in the isocitrate dehydrogenase 1 and 2 genes or express oncogenic fusion proteins between the fibroblast growth factor receptor 2 (FGFR2) gene and several partner proteins." (PMID 39123448, 2024).